SIRAL2 (SIR2 antiphage like 2)
Synonyms: FAM118A; C22orf8; FLJ20635; bK268H5.C22.4
Tractability: Antibody: UniProt predicts a signal peptide or a membrane-spanning region. PROTAC: ubiquitination databases record sites on it.
Gene: Protein-coding gene on chromosome 22 (45,308,968 to 45,342,824, forward strand). Ensembl gene ENSG00000100376.
Subcellular location: Membrane
Subcellular location (Human Protein Atlas): Intermediate filaments; Cytosol
Gene Ontology:
Molecular function: identical protein binding; protein binding
Cellular component: membrane
Genetic constraint (gnomAD): Loss-of-function variants: 21 observed, 35.65 expected, observed/expected ratio (o/e) 0.59, 90% interval 0.42 to 0.85. The upper end of that interval is the gene's LOEUF score, 0.85, which puts it in group 3 of 6, group 1 being the genes least tolerant of losing a copy. Missense variants: 413 observed, 463.22 expected, observed/expected ratio (o/e) 0.89, 90% interval 0.82 to 0.97. Synonymous variants: 176 observed, 185.22 expected, observed/expected ratio (o/e) 0.95, 90% interval 0.84 to 1.08.
Homologues: Orthologues: chimpanzee FAM118A (97% identical), macaque FAM118A (94% identical), dog FAM118A (93% identical), rat Fam118a (93% identical), mouse Fam118a (92% identical), pig FAM118A (91% identical), guinea pig FAM118A (87% identical), rabbit FAM118A (57% identical). Paralogues in human: SIRAL1 (45% identical).
Diseases named in the same sentence as SIRAL2 in open-access papers:
SIRAL2 is named in the same sentence as 13 diseases in open-access papers, as found by Europe PMC text mining. Sharing a sentence is not in itself a finding about the gene and the disease.
SIRAL2 shares sentences with these, for which no sentence is quoted: glioma (2 papers); tumor (2); Achalasia (1); ankylosing spondylitis (1); breast carcinoma (1); cancer (1); dental caries (1); glioblastoma (1); infection (1); inflammatory bowel disease (1); neurologic disorders (1); periodontitis (1); psychiatric disease (1).